BCL2 (BCL2 apoptosis regulator)
Diseases named in the same sentence as BCL2 in open-access papers (continued):
Sharing a sentence is not in itself a finding about the gene and the disease.
cancer (continued). "TG2 in ECM associates with integrins inducing activation of anti-apoptotic protein Bcl-2, focal adhesion kinase (FAK) dependent signal transduction pathways including PI3K/Akt, and Ras/Erk, pathways which contribute to cancer aggressiveness." (PMID 24058567, 2013). "It is well-established that anti-apoptotic proteins such as BCL-2, BCL-XL, and MCL-1 can sequester multiple pro-apoptotic proteins including BIM and BAX to inhibit apoptosis in several cancer types." (PMID 23667527, 2013). "In summary, our finding clearly demonstrated that SSE has anti-cancer activity via suppression of the Akt/mTOR signaling pathway through AMPK activation, which resulted in the down-regulation of Bcl-2 and up-regulation of Beclin-1." (PMID 24053190, 2013). "In the human HCC cancer cell line Huh7, CD133+ CSCs appeared to express higher levels of BCL-2 than their CD133- counterparts." (PMID 23369605, 2013). "On the other hand, miR-34a also has abundance of other targeted miRNAs besides Bcl-2, including SIRT-1, Cyclin D1, Cyclin E2, CDK4, CDK6, E2F3, MET and notch-1, which add to the complexity of the role of miR-34a in human cancers." (PMID 24106980, 2013). "TCN induces G0/G1 cell cycle arrest and apoptosis in cancer cells, activating pro-apoptotic proteins, including caspase-3, -8 and PARP-1, and decreasing the expression of anti-apoptotic proteins Bcl-2, Bcl-xL, and survivin." (PMID 23936501, 2013). "Thus, BCL2 expression could be a valuable predictor of cancer progression and prognosis." (PMID 23637776, 2013). "Four of the down-regulated genes were known cancer genes: KAT2B (from the Ade sequence only), BCL2, IQGAP2 (from Ade & IBD), and PMT (from IBD only)." (PMID 23799036, 2013). "miR-17-5p and miR-143 act as tumor suppressors in cancer cells by targeting TP53INP1 and Bcl-2 respectively." (PMID 23773282, 2013). "The expression of DRs and proapoptotic (Bid, Bax, Bak, Smac/DIABLO) or antiapoptotic (FLIP, Bcl-2, Bcl-xL, Mcl-1, Akt, IAP-1, IAP-2, XIAP, survivin) proteins in cancer cells is involved in TRAIL-resistance." (PMID 23573148, 2013). "EBV also induces upregulation and overexpression of BCL-2 among the B-cells, findings commonly observed in latent EBV infection but also in carcinomas which are EBV positve and EBV+ large B-cell lymphomas." (PMID 23782909, 2013). "The hubs also include RB1, BCL2, AKT1, CDK2, CASP8 which are involved in mechanisms of apoptosis, to which cells are known to acquire resistance in all types of cancers." (PMID 23166660, 2012). "Through blocking the expression of Bcl-2, Bcl-xL, and Survivin with XZH-5, cancer cells displayed enhanced chemosensitivity." (PMID 23056374, 2012). "A subset of the targets (BCL2, CLU, HSPB1, BIRC5, EIF4E and RRM2) is being investigated for cancers in combination with approved cytotoxic drugs." (PMID 22989709, 2012). "Bax/Bcl-2 ratio was significantly increased by treating with MCME for 18 h and was increased with a range from 6.3 to 19.4 at 24 h on different cancer cells." (PMID 23091557, 2012). "Our results showed that Bcl-2 was significantly decreased and Bax was increased in MCME-treated cancer cells." (PMID 23091557, 2012). "Some reported the decrease of antiapoptotic Bcl-2 members, such as Bcl-xL, on GSI treatment in cancer cells." (PMID 22703841, 2012). "Beclin 1, Bcl-2, Bcl-xL, Bad and Bax protein expressions were assessed only in the surgical liver tissues from 13 HCC patients (both in the cancer and in the surrounding cirrhotic tissue)." (PMID 22928777, 2012). "Proliferative program analysis in cancer cells revealed a fundamental impact of CDA-2 and PG on proliferation and apoptosis, including Bcl-2, Bcl-XL, cIAP1, Survivin, PCNA, Ki-67 proteins and TUNEL assays." (PMID 23284890, 2012).
cancer (continued). "Our data revealed that Bcl-2 denitrosylation induced by ZD55-IL-24 triggered the activation of caspase-9, caspase-3, PARP and final carcinoma cell apoptosis from the results of western blotting and flow cytometry." (PMID 22629368, 2012). "Previous reports suggested that t-DARPP provides anti-apoptotic and chemotherapeutic resistance properties to cancer cells through the activation of AKT and up-regulation of Bcl2." (PMID 21447180, 2011). "Small molecule inhibitors of the Bcl-2 family proteins, designed to bind the hydrophobic groove of anti-apoptotic Bcl-2 proteins in place of BH3-only proteins, are potential agents to treat cancers." (PMID 20403207, 2010). "BER has synergistic effects with anticancer agents trichostatin A, celecoxib and carmofur on inhibiting the growth of MDA-MB-231 cells and reducing the ratio of Bcl-2/Bax and/or VEGF expressions in the cancer cells." (PMID 19796390, 2009). "Xuan and Hu reported that Shikonin derivatives circumvented diverse cancer drug resistance (P-gp, MRP1, BCRP1, Bcl-2, Bcl-xL) by inducing a dominant necrosis." (PMID 19594888, 2009). "In cancer cell lines, suppression of DNA MMR has been observed via inhibition of E2F transcriptional activity by Bcl-2." (PMID 19436735, 2009). "Notably, several senolytic compounds aiming to restore apoptotic mechanisms via BCL-2, BCL-XL, and BCL-W inhibition in cancer cells are currently undergoing clinical trials, highlighting their potential as adjuvants in cancer management." (PMID 41557725, 2026). "Previous research from our laboratory demonstrated that proTAME-containing therapies reduced CDC20 expression and increased the Bax/Bcl-2 ratio in RT4 cells, promoting apoptosis, while reducing this ratio in ARPE-19 cells, indicating a selective effect on cancer cells." (PMID 40136519, 2025). "We identified two pro-proliferative genes whose protein expression increased upon BCL2 inhibition, FGFR3 (log2ratio = 0.87, p-value = 2.00E-03) and MTOR (log2ratio = 0.53, p-value = 3.49E-02), which have well-known roles in cancer signaling, i.e., FGFR signaling, and mTOR signaling." (PMID 40568132, 2025). "Additionally, PCR results reveal that PSME2 and PSMB8 are highly expressed in cancer tissues, while BMP5 and BCL2 are more highly expressed in normal tissues." (PMID 41403941, 2025). "In addition, fisetin significantly modulated the level of cancer-related genes such as those involved in the PI3K/AKT/mTOR pathway, apoptotic genes, BAX and BCL-2, and the transcription factor gene NF-κB." (PMID 41180483, 2025). "To determine whether the downregulation of BCL-2 by DNZ-15 and DNZ-35a translated into functional anti-cancer effects, we assessed cell viability and apoptosis induction in vitro." (PMID 40643466, 2025). "The docking results of caffeic acid (CA) and benzyl isothiocyanate (BITC) with key cancer-related receptor proteins—including ERK2 (PDB: 4QTB), p38 MAPK (PDB: 3GCU), Bcl-2 (PDB: 4MAN), Keap1-Nrf2 complex (PDB: 5YWE), and GST (PDB: 1ZHA)—revealed strong binding interactions." (PMID 40799801, 2025). "BH3 mimetic drugs that selectively target the pro-survival BCL2 proteins are highly promising for cancer treatment, most notably for treating blood cancers." (PMID 40204951, 2025). "The link between Caspase‐8 and Bcl‐2 may be disrupted by the SPARC peptide, which can restore sensitivity in chemoresistant cancers." (PMID 40415238, 2025). "Additionally, the general pathways in cancer involve 13 genes (FDR of 2.49 × 10−5), including oncogenes and signalling molecules like PKAc, AKT3, and BCL2, which play essential roles in cellular growth and survival mechanisms." (PMID 40699738, 2025).
cancer (continued). "However, only AKT1, EGFR, BCL2, HSP90AA1, and PTGS2 exhibited strong binding affinities with pomegranate compounds, which are significantly declared in affected cells to enhance cancer progression." (PMID 40573291, 2025). "Since this compound targets both BCL-2 and MCL-1—important for short-term and long-term anti-apoptotic defenses, respectively—its dual action supports that it is effective against aggressive and resistant cancer subtypes." (PMID 39859117, 2025). "However, in cancer, as there are variations in the levels of proteins and enzymes related to apoptosis, including BAX, BCL-2 and Caspase-3 on the apoptotic pathway, apoptosis is inactivated and the rapid progression of cancer continues." (PMID 41614842, 2025). "Moreover, the levels of downstream molecules (including p-eIF4E, cyclin D1, snail, and Bcl2) regulated by RACK1 were also decreased after SENP3 knockdown, which is consistent with the impact of SENP3 on cancer hallmarks." (PMID 39755756, 2025). "Although increased priming correlated with increased sensitivity to BCL-2/BCL-xL inhibition in certain contexts, TIS cancer cells generally exhibited similar or reduced overall priming compared to their proliferative counterparts, revealing a nuanced apoptotic landscape." (PMID 40055336, 2025). "Overexpression of Bcl‐2 protein is found in more than half of all cancers, regardless of their type." (PMID 40666823, 2025). "The bioactivity test showed that serratiochelin B displayed weak but selective cytotoxicity against HepG2 cancer cells with an IC50 of 50.6 μmol/L and could trigger apoptosis through both Bcl-2/Bax/caspase-3 and Fas/FasL/caspase-8 signaling pathways." (PMID 40559650, 2025). "This is an important capability, as there is strong concern about patient resistance to Venetoclax that is thought to be mediated by changes in cancer cells’ dependencies from one BCL-2 family protein to another, for instance, from BCL2 priming to MCL1 priming." (PMID 40507334, 2025). "The inhibition of VEFGA results in the reduction of MAPK phosphorylation and the downregulation of the anti-apoptotic marker BCL-2, indicating that targeting VEGFA may represent a viable therapeutic option in the context of cancer." (PMID 40702566, 2025). "For instance, the co-delivery of Bcl-2 siRNA and DXR using cationic liposome-incorporated poly(ε-caprolactone)/chitosan nanofibers demonstrated a synergistic effect, significantly increasing cancer cell death in vitro utilizing the A2780/AD human cancer cells." (PMID 41007213, 2025). "NSD2 has been shown to play a role in cancer progression by regulating key oncogenes, such as cyclin D1 (CCND1), MYC proto‐oncogene, BHLH transcription factor (MYC), and BCL2 apoptosis regulator (BCL2), which contribute to cell survival and proliferation." (PMID 40386826, 2025). "However, the overexpression of BCL-2 can antagonize BAX, allowing cancer cells to evade apoptosis and continue proliferating." (PMID 39966442, 2025). "It is also likely that there will not be just one treatment for each class, but rather that defining a cancer as either YAPon or YAPoff will direct you towards a subset of drugs - e.g., kinase or YAP/TEAD inhibitors for YAPon cancers and BCL2, XPO1, NAMPT or epigenetic inhibitors for YAPoff cancers." (PMID 40440076, 2025). "TAS-115 markedly inhibited cancer cell proliferation, as shown by reduced GFP+ MDA-MB-231 cell populations, and induced apoptosis via upregulation of Bax and Caspase-3, alongside suppression of Bcl-2 expression." (PMID 41289612, 2025). "In addition to its role in EMT, Slug was shown to inhibit apoptosis in cancer and other cells by transactivating the expression of PUMA, Bcl-2 and Bax, thereby exerting an anti-apoptotic effect." (PMID 40427135, 2025).
cancer (continued). "Bcl2 prevents mitochondrial membrane permeabilization, a critical step in apoptosis initiation, and its downregulation following RCC1 knockdown underscores RCC1’s role in modulating anti-apoptotic mechanisms to promote cancer cell survival." (PMID 40163507, 2025). "An overexpression of Bcl-2 has been observed in more than 50% of cancer cases, regardless of subtype." (PMID 40002709, 2025). "Cancer cells may also enhance the expression of anti-apoptotic proteins, including MCL-1 and BCL-2, which are known to confer resistance to CDK inhibitors by suppressing apoptotic signaling." (PMID 40076816, 2025). "Other genes, such as NLRP3, BCL2, and TIM4, are also affected by MPs in the mentioned cancer." (PMID 41378310, 2025). "This study demonstrates that carvacrol exerts multi-targeted anticancer effects in both HR+ (MCF-7) and TNBC (MDA-MB-231) BC cells by enhancing the BAX/BCL2 ratio, inducing apoptosis, reducing oxidative stress, and downregulating CD44+ cancer stem cell marker levels." (PMID 41154846, 2025). "In both in vivo and ex vivo cancer models, the combination of quercetin and metformin resulted in caspase-dependent apoptosis, as well as reduced invasion and activity of Akt/PI3K, VEGF, and Bcl-2." (PMID 40143065, 2025). "In addition, the effects of this formulation on cell apoptosis, cell adhesion, cancer cell migration, and BAX, Bcl‐2, and Caspase‐3 gene expressions were evaluated using flow cytometry, atomic force microscopy, scratch, and q‐real time PCR, respectively." (PMID 40444124, 2025). "These non-apoptotic functions of BCL-2 proteins have broad implications for cell physiology and are critical in many diseases beyond cancer, including neurodegeneration, cardiovascular disorders, and immune system dysregulation." (PMID 40204952, 2025). "Reduced β-catenin expression along with both BCL2 and HSP90 results in better overall survival for carcinoma patients, thus rendering such molecular markers as prognostic factors for survival of patients following their inhibition using targeted inhibition therapy." (PMID 40456804, 2025). "Mcl-1 inhibits apoptosis by heterodimerizing with pro-apoptotic Bcl-2 members via its BH3 domain and is upregulated in several cancers, including lung, breast, colon, ovarian carcinoma, and gastric cancer, mediating resistance to apoptosis induced by conventional chemotherapy and targeted therapy." (PMID 38928234, 2024). "The anti-cancer properties of AgNPs have been demonstrated in previous studies against several cancer cell lines; it has been hypothesized that these compounds might inhibit AMPK/mTOR signalling and BCL-2 expression." (PMID 38575697, 2024). "Consistent with the effects on the cancer cell growth and survival, knockdown REV-ERBα strongly decreased expression of proteins important for growth, proliferation, and survival including MYC, CDK4, CDK6, CCND2/D3, and BCL2." (PMID 39383000, 2024). "YBX1 has predictive value for drug resistance and poor prognosis in more than 20 cancer types, and upregulates the expression of multiple drug resistance genes, including ABCB1, MVP/LRP, TOP2A, CD44, CD49f, BCL2, and MYC, upon UV irradiation or Cisplatin treatment." (PMID 39168971, 2024). "For example, by modulating Bcl-2, PGAM1 could influence apoptotic pathways, while its interaction with Snail could impact the EMT process, a critical step in cancer metastasis." (PMID 38434965, 2024).
cancer (continued). "Importantly, the main anti-apoptotic proteins BCL-2, B-cell lymphoma-extra large (BCL-XL) and myeloid cell leukaemia 1 (MCL-1) are often upregulated across many adult and paediatric cancer types." (PMID 38942989, 2024). "The developed system encapsulated three different agents: adriamycin, as a cancer chemotherapeutic, as well as MVP-siRNA and BCL2-siRNA to inhibit the major vault protein (MVP) and the B-cell lymphoma-2 (BCL2) gene which are responsible for the multidrug resistance exhibited by the specific cells." (PMID 39065565, 2024). "Thus, exogenous umbilical cord-derived MSCs can inhibit growth and promote the apoptosis of cancer cells by downregulating AFP, Bcl-2, and survivin." (PMID 38660138, 2024). "The apoptotic effect of BFC1108 is not inhibited, but rather potentiated, by Bcl-2 expression in multiple cancer cell lines." (PMID 38329389, 2024). "In order to determine whether LP treatment induces apoptotic cell death in HaCaT, A375, and MCF-7 cancer cells, the pro-apoptotic BAX and anti-apoptotic Bcl-2 levels were quantitatively measured using an in vitro enzyme-linked immunosorbent assay (ELISA)." (PMID 38258008, 2024). "Bcl-2, Bax, IL-6, AKT, and P38 play a role in cancer progression." (PMID 38072891, 2024). "Overexpression of BCL2 in 73% of BCas, with 86% in estrogen receptor-positive (ER+) tumors, nominates BCa as the first non-hematologic cancer type to be targeted with BCL2 inhibitors." (PMID 39605038, 2024). "Simultaneous targeting of BH3 domain:hydrophobic groove and the TMD interface of Bcl-2 proteins, therefore, harbors not yet exploited potential for anti-cancer therapy, for example, by increasing drug specificity." (PMID 39048751, 2024). "In studding apoptotic pathway, Bcl2 expression was significantly increased in cancer tissue compared with non-cancerous tissue (p < 0.001)." (PMID 38072891, 2024). "Additionally, LINC01405 upregulation led to the increased cell populations, proliferation, and upregulation of critical cancer‐related genes, including AKT1, AKT3, mTOR, WNT3A, SMAD3, CYCLIN D1, CYCLIN D2, BCL2, and GSK3B." (PMID 38225865, 2024). "Concurrently, CP and PAL can also increase ERK1/2 activity in cancer cells, leading to LC3 activity, which, in coordination with JNK inhibiting bcl2 to release beclin 1 and upregulating autophagy-related protein 5 (ATG5), leads to the development of the nascent autophagosome." (PMID 38785562, 2024). "Additionally, APS opposed the activation of NF-κB and decreased the expression of anti-apoptotic genes such as Bcl-2, Bcl-xL, and IAP family members, enhancing cancer cell sensitivity to chemotherapy." (PMID 38794206, 2024). "In vivo and in vitro experiments revealed that these active components significantly induced apoptosis in cancer cells, markedly reduced the expression of p-EGFR, HSP90, p-AKT, p-PI3K, and bcl-2, and increased the expression of ppar, bax, cleaved caspase 3, and cleaved PARP." (PMID 39274982, 2024). "While, DTX has shown to regulate BAX/BCL-2 ratio instead only suppressing the BCL-2 expression in a dose and time-dependent manner, miR-34a is well reported to downregulate the BCL-2 translation in cancer as well as neurodegenerative diseases." (PMID 39289425, 2024).